CDC7 (cell division cycle 7)
Diseases named in the same sentence as CDC7 in open-access papers (continued):
Sharing a sentence is not in itself a finding about the gene and the disease.
cancer (continued). "As CDC7 is frequently overexpressed in a variety of human malignancies, it is a desirable target for cancer treatment." (PMID 40136426, 2025). "Several CDC7 inhibitorshave been developed and evaluated in preclinical studies, showingencouraging efficacy across various cancer models, including thoseresistant to standard therapies." (PMID 39829445, 2025). "As a proof-of-concept, miRTARGET identified CDC7 and its regulatory unit DBF4 as the top cancer-associated predicted targets of the tumor suppressive miRNA miR-30a." (PMID 40561849, 2025). "CDC7 inhibitors, such as XL413, have been a breakthrough in the therapeutic treatment of cancer therapy because they can cause tumor cell cycle blockage, which stops the growth of tumor cells." (PMID 40136426, 2025). "As shown in previous research, CDC7 is overexpressed in a large number of primary tumors and cancer cells, and this overexpression profile helps the cells withstand chemicals that damage DNA." (PMID 40136426, 2025). "CDC7 has been found overexpressed in many cancer cell lines and certain primary tumours like ovarian, breast, liver, colon cancer, lung adenocarcinoma and melanoma." (PMID 38205514, 2024). "Cell division cycle 7 kinase (CDC7) has been found overexpressed in many cancer cell lines being also one of the kinases involved in the nuclear protein TDP-43 phosphorylation in vivo." (PMID 38205514, 2024). "Due to its known roles in the initiation of DNA replication and DNA damage response, CDC7 has been considered a promising therapeutic target in cancer, for which a number of inhibitors are under investigation." (PMID 39054323, 2024). "CDC7 expression is minimal or undetectable in normal tissues and cell lines but highly expressed in many human cancer and tumor cell lines." (PMID 38468345, 2024). "Novel therapies targeting replication regulatory molecules, such as PARP, ATR, CHK1, and CDC7, are being energetically developed for the next generation of RS-inducing cancer drugs." (PMID 37980406, 2023). "As a whole complex member and elevated in most cancer types, DBF4 and CDC7 were found positively correlated with each other in 26 TCGA cancer types, especially in HCC." (PMID 36609254, 2023). "Cell division cycle 7 (Cdc7) is a serine/threonine kinase that gained considerable interest as a promising target in cancer therapy because it plays a vital role in the initiation and preservation of DNA replication in eukaryotic cells." (PMID 37513232, 2023). "Both DDK subunits, Cdc7 and Dbf4, are frequently found to be overexpressed in cancer and this is correlated with cancer development and poor prognosis." (PMID 35614055, 2022). "In terms of prognosis, a high percentage of CDC7-positive cells has been reported in several cancers, including DLBCL, and correlates with a poor prognosis." (PMID 36426371, 2022). "Increased CDC7 expression has been observed in primary malignant tumors such as breast, colorectal, and also head and neck cancers, which has led to this protein being considered as a therapeutic target." (PMID 36483932, 2022). "In the cancer genome atlas (TCGA), CDC7 expression was lower in samples from normal persons compared with that in samples from persons with DLBCL, based on gene expression profiling and interactive analyses (P < 0.05)." (PMID 36426371, 2022). "Inhibition of the Cdc7/Dbf4 kinase activity can affect specific phosphorylation sites on MCM2 in cancer cells." (PMID 34975331, 2022).
cancer (continued). "TAK-931 (simurosertib) is an oral, highly potent, selective kinase inhibitor of CDC7 with demonstrated replication, stress-mediated antiproliferative activity across various cancer cell lines." (PMID 36970056, 2022). "The use of small molecule Cdc7 inhibitors have enabled interrogation of the role of DDK as a molecular target in cancer therapy and in the regulation of DNA replication origin activation." (PMID 36009559, 2022). "Inhibition of such overexpression can then be used to treat certain cancers; therefore, CDC7 has become a meaningful target for cancer treatment." (PMID 33763482, 2021). "CDC7 is a kinase playing a crucial role in the initiation of DNA replication, and many cancer types and tumor cell lines are rather up-regulated." (PMID 34298942, 2021). "CDC7 is frequently overexpressed in various human cancers, making it an attractive therapeutic target for cancer treatment." (PMID 34881526, 2021). "CDC7 regulates the G1/S transition, and its overexpression is a common occurrence in multiple human cancers." (PMID 34366863, 2021). "CDC7 is a crucial kinase required for initiating the replication machinery, and its overexpression has been reported in various cancers." (PMID 33801812, 2021). "Currently, Cdc7 inhibitors are in clinical trials to downregulate Cdc7 activity in cancer cells (clinicaltrials.gov #’s NCT02699749, NCT03096054)." (PMID 32295767, 2020). "Targeting Cdc7 through siRNA knockdown in cancer cells has been shown to result in cancer cell-specific apoptotic cell death, whereas non-cancerous cells arrest in G1 and resume proliferation after Cdc7 activity is restored." (PMID 32295767, 2020). "Inhibition of CDC7 kinase activities resulted in cancer cell-specific apoptosis as a consequence of abrogation of cell cycle progression." (PMID 31578454, 2019). "Our results indicate higher dependency on Cdc7 for checkpoint activation in cancer cells than in non-cancer cells." (PMID 31889509, 2019). "It was later reported that Cdc7 inhibition using an inhibitor delayed the checkpoint activation in cancer cells." (PMID 31889509, 2019). "The results indicate that the numbers of Cdc7 molecules in cancer cells are 10–50 fold more than those in non-cancer cells." (PMID 31889509, 2019). "In summary, our findings in this report show that Cdc7 is a major kinase that mediates phosphorylation of CKBD of Claspin in response to replication stress, especially in Cdc7-overexpressing cancer cells." (PMID 31889509, 2019). "The following results presented in this study show that Cdc7 is predominantly responsible for phosphorylation of CKBD of Claspin in response to replication stress in most of the cancer cells." (PMID 31889509, 2019). "We also showed siRNA-mediated inhibition of Cdc7 expression resulted in significant reduction of Chk1 activation in cancer cells." (PMID 31889509, 2019). "Here, we show that Cdc7 is required for Claspin-Chk1 interaction in human cancer cells by phosphorylating CKBD (Chk1-binding-domain) of Claspin." (PMID 31889509, 2019). "In our experiments, T cells were sensitive to Cdc7/Cdk9 inhibition in the range of concentrations similar to those reported for cancer cells." (PMID 31402912, 2019). "This is consistent with the fact that, in cancer cells, Cdc7 depletion inhibits checkpoint activation more vigorously than CK1γ1 depletion does, and that combination of both depletions results in almost complete inhibition of checkpoint activation." (PMID 31889509, 2019). "The Cdc7/Cdk9 inhibitor is a strong candidate as a cancer therapeutic, but its effect on the immune system poses a problem for clinical applications." (PMID 31402912, 2019). "Cdc7 and Cdk9 are seen as promising targets in cancer, and multiple compounds targeting these kinases, including PHA-767491, have been investigated for potential anti-cancer effects in preclinical studies and clinical trials." (PMID 31402912, 2019).
cancer (continued). "Later, requirement of Cdc7 for timely checkpoint activation in cancer cells was confirmed by using a compound that inhibits Cdc7 kinase." (PMID 31889509, 2019). "In cancer cells, we consistently observed that Cdc7 depletion reduced Chk1 activation more than CK1γ1 depletion did." (PMID 31889509, 2019). "We noted that the levels of Cdc7 were significantly lower in these latter cell lines than in other cancer cell lines." (PMID 31889509, 2019). "Cdc7 is found to be up-regulated in various cancers and has been characterized as an independent prognostic marker and a potential therapeutic target." (PMID 30062004, 2018). "Of interest, many of the identified candidate proteins belong to protein families that already have cancer‐associated members (such as MCM6 and MCM7 proteins, MAPK8, or CDC7)." (PMID 29572294, 2018). "We previously found that increased Cdc7 inhibits DNA damage-induced apoptosis and increases the survival of cancer cells upon DNA damage response." (PMID 29209046, 2017). "For example, PHA-767491 (Nerviano Medical Sciences, Nerviano, Italy), a dual Cdc7/Cdk9 inhibitor, has been shown to have activity by inducing apoptosis in a wide variety of cancer cell lines." (PMID 26921250, 2016). "The cancer specific killing following Cdc7 targeting has generated great interest in the development of therapeutic Cdc7 small molecule inhibitors." (PMID 26921250, 2016). "CDC7 overexpression is present in different cancers, and small molecule inhibitors of the CDC7 have well-documented anti-tumor effects." (PMID 27891063, 2016). "In a study of 62 human cancer cell lines, Cdc7 was found to be increased in ~50% of these lines relative to β-actin with levels in normal primary cell lines either very low or absent." (PMID 26921250, 2016). "Clinically, in many kinds of cancers, CDC7 upregulation is related to tumor anaplasia, aneuploidy, advanced disease stage and lower relapse-free survival." (PMID 25475780, 2015). "Cell cycle kinases (e.g. CDC2, CDC5, CDC7 and CDC20) as well as AURKA and S100A9, which can all broadly be linked to cell cycle regulation and mitosis, were upregulated in the malignant tumors." (PMID 25226589, 2014). "This novel mechanism for regulating Cdc7 function provides an explanation for previous contradictory results concerning the control of Cdc7 by checkpoint kinases and has implications for the use of Cdc7 inhibitors as anti-cancer agents." (PMID 24403013, 2014). "Our data also suggest that the regulatory mechanism of CDC7 by miR-630 is operative in cancer and immortalized cells, in particular when exposed to DNA-damaging agents." (PMID 25255219, 2014). "The cell division cycle 7 (CDC7) is an essential S-phase kinase and emerging CDC7 inhibitors are effective in a variety of preclinical cancer models." (PMID 24202326, 2013). "PHA-767491 is the prototype CDC7 inhibitor and has been shown to have activity in many preclinical cancer models." (PMID 24202326, 2013). "In this study, we analyzed the effect of Cdc7 depletion in cancer cells by using the recently developed cell cycle indicator Fucci as well as similar fluorescent cell cycle indicators." (PMID 22574151, 2012). "The combination of Cdc7 inhibition with known anti-cancer agents significantly stimulates cell death effects in cancer cells in a genotype-dependent manner, providing a strategic basis for future combination therapies." (PMID 22574151, 2012).
cancer (continued). "Because of its importance in cell cycle progression, Cdc7 is being exploited as a therapeutic target in cancer." (PMID 22384342, 2011). "A new CDC7 inhibitor called XL413 has demonstrated promising antitumor therapeutic effects in a variety of malignant tumors and may have anticancer properties." (PMID 40136426, 2025). "Newly available CDC7 inhibitors have shown efficacy in various types of cancer and could be effective in treating adeno-CRPC and in preventing the transition to NEPC25,26." (PMID 41413594, 2025). "Moreover, a novel treatment plan for cancer that involves oxaliplatin and the CDC7 inhibitor XL413 was released." (PMID 40136426, 2025). "The therapeuticpotential is substantial, as targeting CDC7 could enable the selectivedestruction of cancer cells while preserving normal tissues, ultimatelyimproving treatment outcomes and reducing side effects." (PMID 39829445, 2025). "Considering this background, the main objective of this work is to identify new allosteric binding sites on the surface of CDC7 and discover new allosteric modulators as a new and powerful strategy to regulate protein function for the treatment of cancer and neurological conditions." (PMID 38205514, 2024). "This speculation was further confirmed by pearson and GSEA analysis, the genes highly associated with CDC7 and DBF4 are enriched in cell cycle, DNA replication and microRNA in cancer pathways." (PMID 36609254, 2023). "Both ATR and CDC7 inhibitors (ATRis and CDC7is) show excellent anti-tumor activity in a variety of preclinical cancer models and are currently being explored as potential anti-cancer agents in clinical trials." (PMID 37378325, 2023). "Therefore, CDC7 is a therapeutic target molecule for cancer therapy, and various CDC7 inhibitors have been developed." (PMID 37517032, 2023). "It has been speculated that CDC7 would inhibit genotoxin-induced apoptosis and protect cancer cells upon DNA damage response, so that it would enhance chemotherapy resistance." (PMID 35708873, 2022). "Inhibition of DDK activity causes apoptosis in cancer cells, but not in normal cells, and therefore Cdc7 is seen as an attractive therapeutic target." (PMID 35614055, 2022). "We reexamined this in human cancer cell lines by knocking down Cdc7 expression with siRNA." (PMID 31889509, 2019). "Future research could explore whether blocking Cdc7 could stop Chk1 activation in cancer cells only." (PMID 31889509, 2019). "The DE/A mutant of AP (APDE/A) in which all the acidic residues in AP were replaced with alanine is deficient in interaction with Cdc7 and fails to support phosphorylation of Mcm in non-cancer cells." (PMID 31889509, 2019). "Cell division cycle-7 protein is a serine/threonine kinase that has a basic role in cell cycle regulation and is a potential prognostic or therapeutic target in some human cancers." (PMID 29339028, 2019). "An early report on the therapeutic effect of Cdc7 inhibition suggested that chemical interference with Cdc7 may predominantly target cancer cells." (PMID 31402912, 2019). "The dependency of Chk1 kinase activation on each kinase differs between cancer cells and non-cancer cells; cancer cells expressing a high level of Cdc7 exhibit higher dependency on Cdc7, whereas non-cancer cells with a lower level of Cdc7 depend more on Chk1γ1." (PMID 31889509, 2019). "CDC7 inhibitors have a major potential as new generation of anti-cancer targeted therapies." (PMID 31578454, 2019). "Consequently, although therapeutic inhibition of Cdc7 and Cdk9 continues to provide opportunities in cancer, their impact on the immune system warrants further consideration for clinical application." (PMID 31402912, 2019). "Cdc7 and Dbf4 are overexpressed in many types of cancer including oral cancer." (PMID 29209046, 2017).
cancer (continued). "Small molecule inhibitors of CDC7 were shown to have anti-tumor activity in different cancer types." (PMID 27891063, 2016). "Similar effect of etoposide on cancer cell death induced by Cdc7 depletion was previously reported." (PMID 22574151, 2012). "The CDC7 kinase could serve as atarget for therapeutic intervention in cancer." (PMID 38107948, 2023). "Thus, CDC7 could represent a novel therapeutic target and is an active area of research in cancer therapy." (PMID 36409435, 2023). "Targeting Cdc7 may be of clinical significance in cancer therapy." (PMID 36009559, 2022). "Thus, Cdc7 has emerged as an attractive drug target for cancer therapy." (PMID 35296675, 2022). "Cdc7 is overexpressed in a number of cancers and may represent a prognostic marker." (PMID 31402912, 2019). "Taken together, we suggest that overexpression of Cdc7 not only causes more DNA lesions to activate checkpoint and HR DNA repair during the early stage of replication stress but also triggers TLS and replication restart as a compensatory mechanism for the survival of cancer cells." (PMID 29209046, 2017). "Therefore, Cdc7-Dbf4 may perform its kinase activity to phosphorylate its downstream substrates to regulate checkpoint function to enhance the survival of cancer cells under replication stress." (PMID 29209046, 2017). "Moreover, CDC7 overexpression is present in different cancer types." (PMID 27891063, 2016). "Therefore, varying oncogenic properties of Cdc7 might also be attributable to differing molecular backgrounds in various cancer types." (PMID 26208856, 2015). "Additionally, the prognosis for cancer may be improved when combined with the CDC7 inhibitor XL413." (PMID 40136426, 2025). "Cell division cycle 7 (CDC7), a serine‐threonine kinase, is required to initiate DNA replication, and inhibition of CDC7 impairs cancer cell growth through S phase." (PMID 39372390, 2024). "Claspin facilitates initiation by recruiting Cdc7 and thereby promoting MCM phosphorylation, notably in non-cancer cells." (PMID 39194567, 2024). "As a result of further study of the Chk1 binding domain of phosphorylated CLSPN, it has been established that Cdc7 is necessary for the interaction between CLSPN and Chk1 in human cancer cells." (PMID 38256171, 2024). "Recent studies have established the CDC7-specific small-molecule inhibitor, TAK-931, as a clinical candidate that exhibits RS-induced antiproliferation in a broad range of cancer cells." (PMID 37980406, 2023). "The CDC7-specific inhibitor, TAK-931, was successfully developed as a next-generation RS-inducer for cancer drug candidates." (PMID 37980406, 2023). "Studies have shown that Cdc7-Dbf4 (Dbf4-dependent kinase; DDK) overrides replication stress in cancer cells to promote replication, which can be reversed using DDK inhibitors to promote fork stalling and cell cycle arrest." (PMID 35850776, 2022). "Based on our results for SDL of GALCSE4 in cdc7-7 strains, we propose that inhibition of Cdc7 in cancers with high levels of CENP-A would lead to cancer cell-specific cell death." (PMID 32295767, 2020). "Non-cancer cells including NHDF, RPE-1, and TIG-3 exhibited more dependency on CK1γ1 than on Cdc7 for checkpoint activation." (PMID 31889509, 2019). "The results suggest a possibility that Cdc7 predominantly serves as a CKBD kinase in the majority of cancer cells, since it is overexpressed, whereas in NHDF, CK1γ1 is more abundant than Cdc7, and thus serves as a major kinase for CKBD phosphorylation." (PMID 31889509, 2019). "Inhibitors of CDC7 and CDC20 kinases would be promising candidates for novel classes of cancer drugs." (PMID 30363964, 2018).